RNU6-1137P (RNA, U6 small nuclear 1137, pseudogene)
Gene: Small nuclear RNA gene on chromosome 17 (43,395,993 to 43,396,091, reverse strand). Ensembl gene ENSG00000252882.
Homologues: Orthologues: chimpanzee U6 (99% identical), mouse Gm23856 (67% identical), rabbit U6 (63% identical), dog U6 (62% identical), guinea pig U6 (60% identical). Paralogues in human: RNU6-259P (78% identical), RNU6-1011P (77% identical), RNU6-1075P (77% identical), RNU6-1145P (77% identical), RNU6-166P (77% identical), RNU6-29P (77% identical), RNU6-407P (77% identical), RNU6-41P (77% identical), RNU6-456P (77% identical), RNU6-558P (77% identical), RNU6-589P (77% identical), RNU6-1060P (76% identical), and 1289 more.